VHL (von Hippel-Lindau tumor suppressor)
Diseases named in the same sentence as VHL in open-access papers (continued):
Sharing a sentence is not in itself a finding about the gene and the disease.
tumor (continued). "Numerous mutations of the Von Hippel-Lindau (VHL) gene have been reported to cause dysfunction of VHL protein (pVHL) and lead to processes related to tumor progression." (PMID 27517496, 2016). "Ectopic Dicer expression in VHL-deficient ccRCCs suppressed tumor growth and angiogenesis by inhibiting HIF-2α both in vitro and in vivo." (PMID 26943772, 2016). "A major question that arises from our findings involves the timing of VHL loss and how it impacts tumour behaviour." (PMID 27358011, 2016). "Loss-of-function and alterations of the von Hippel Lindau (VHL) tumor suppressor gene have been found in at least two-thirds of sporadic clear cell RCC (ccRCC) tumor tissue, and germline mutations involved in hereditary ccRCC as well." (PMID 26848523, 2016). "Sequencing of VHL in primary tumors and cultures verified a patient tumor-matching VHL mutation in RCC22 cells grown in FBS, while the remaining lines did not recapitulate the patients’ tumor VHL mutations." (PMID 27422173, 2016). "On the other hand, recent investigations suggest that, the tumor suppressor VHL mutation in mice enhanced expression of key HIF-2α genes, then promoted splenic erythropoiesis." (PMID 27708244, 2016). "Using RT-PCR for Cas9 and eGFP, circulating tumour cells were significantly increased in the peripheral blood of animals implanted with cells deficient in VHL." (PMID 27358011, 2016). "It is caused by germline mutations in the VHL tumor suppressor gene, located on the short arm of chromosome 3." (PMID 27527340, 2016). "ccRCC is a dominant subtype of kidney cancers in most of which the von Hippel-Lindau (VHL) tumor-suppressor gene is mutated or lost." (PMID 27438705, 2016). "Considering that the hypoxia, angiogenesis and erythropoiesis pathways are conserved between humans and fish, the zebrafish serves as an excellent model to study VHL-associated tumor biology." (PMID 27491085, 2016). "Inactivation of VHL, which occurs through mutation, deletion, or methylation, causes the accumulation of HIFα under normal oxygen conditions and encourages tumour growth." (PMID 26448938, 2015). "ccRCC develops in the renal proximal tube and is linked to biallelic inactivation of the VHL tumor suppressor gene." (PMID 26579493, 2015). "Apart from its role in HIF turnover, VHL is also a tumour suppressor, the loss of which causes VHL-associated polycythaemia disease (an increase in red blood cell count) in humans." (PMID 26512123, 2015). "The VHL tumor suppressor gene contains 3 exons, encoding a protein of 213 amino acid residues, known as pVHL3010." (PMID 26211615, 2015). "Collectively in case of three missense mutations of VHL gene (V155A, L158Q, and Q164R), they had function of tumor suppressor if they were protected from degradation." (PMID 26503325, 2015). "Recent comprehensive genomic analyses of ccRCC revealed in addition to VHL mutations, recurrent mutations in several other ccRCC tumor suppressor genes including PBRM1, SETD2, and BAP1." (PMID 25826081, 2015). "Heterozygous mutation of VHL in humans predisposes affected individuals to the development of highly vascularised tumours and cysts upon loss of heterozygosity of the remaining VHL allele, this is known as VHL disease." (PMID 26559940, 2015). "Distinctive from anti-angiogenic agents that target the neovasculature resultant from uncurbed HIF expression in VHL mutated cases, compound that targets the VHL mutated tumour cell itself appears intriguing." (PMID 25853938, 2015). "Patients are heterozygous for mutations in VHL, a tumor suppressor gene located on the short arm of chromosome 3 (3p25–p26)." (PMID 26394686, 2015). "In different types of tumours, even in conditions of normoxia, the HIF-1α protein levels are elevated, resulting from loss-of-function mutations targeting its negative regulator VHL tumour suppressor." (PMID 26339588, 2015).
tumor (continued). "The resultant upregulation of hypoxia inducible factors (HIF1α and HIF2α, also known as HIF1A and EPAS1) due to failure of ubiquitination by the mutated VHL leads to vast neovasculature, which subsequently promotes tumour growth." (PMID 25853938, 2015). "There is increasing evidence that the “second hit” causes loss of pivotal VHL function during organ development leading to maldeveloped structures that represent prerequisites for tumor formation." (PMID 28326266, 2015). "Taken together, these results show that MDN-0066 selectively kills RCC cells with a loss of VHL in vitro and also significantly reduces tumor growth in VHL-deficient cells." (PMID 26018559, 2015). "A characteristic found in all ten tumours was the presence of inactivating somatic alterations in the von Hippel Lindau (VHL) gene and loss of heterozygosity of chromosome 3p, harbouring the second copy of the VHL gene, on the trunk of the phylogenetic trees." (PMID 25555261, 2015). "Several reports have demonstrated a direct correlation between the loss of VHL expression and alterations in the cellular metabolism, leading to an altered tumor microenvironment, such as high lactate concentrations and low pH value." (PMID 25890500, 2015). "In the current study, we have used 2 major databases to identify a compound, TGX221 not previously studied in ccRCC that has strong selectivity for tumours having VHL, SETD2, PTEN and CDKN2A mutations." (PMID 25853938, 2015). "Von Hippel–Lindau syndrome is an autosomal dominant disease associated with inactivating mutations in the VHL tumor suppressor gene located on chromosome 3." (PMID 26347711, 2015). "Clusters Mi1 and Mi2 comprised SDHx- and VHL-mutated tumours, respectively, whereas cluster Mi3 was enriched in sporadic tumours belonging to the C2B mRNA expression cluster." (PMID 25625332, 2015). "Mutations that inactivate VHL protein have been associated with a variety of tumor systems including clear-cell renal-cell carcinoma, pheochromocytoma, pancreatic tumors, central nervous system, and retinal hemangioblastoma." (PMID 26561808, 2015). "VHL’s function as tumor suppressor requires its association with a ubiquitous complex composed of two small proteins, Elongin B and Elongin C, via a linear sequence termed the “BC box,” comprising amino acids 157–172." (PMID 26561808, 2015). "c) Since VHL deficient tumor cells in nervous system have been identified as hemangioblastic progenitor cells, an origin from VHL-deficient stem cells with hemangioblastic differentiation potential certainly deserves consideration." (PMID 28326266, 2015). "Release of VHL from TRiC requires VHL binding to Elongin B and C and is impaired by tumor-producing mutations that affect the BC-binding site." (PMID 26561808, 2015). "The relationship between mutations of VHL and KIRC has been established for decades and the association between VHL and tumor stage, tumor-cell proliferation, and patient prognosis has also been well studied." (PMID 26148869, 2015). "The recent identification of numerous VHL-deficient DASEs in tumor-free CNS tissues of VHL patients led to the conclusion that the “second hit” is necessary, but insufficient for tumorigenesis." (PMID 28326266, 2015). "Other altered genes, which cooperate with the VHL gene loss of function to initiate tumor development, should also be identified." (PMID 26210994, 2015). "The CXCR4 gene can further be transactivated by the activation of hypoxia-inducible factor- (HIF-) 1α, arising either from loss of the von-Hippel-Lindau tumor suppressor (VHL) or due to the hypoxic conditions observed frequently in tumor tissues." (PMID 24966464, 2014). "Among the hybrid tumor 03 cases with foci of clear cells show VHL mutations while a single case showing combination of clear cells and chromophobe cells was negative for mutations." (PMID 25097537, 2014).
tumor (continued). "The results indicate that the decrease of VHL expression associates with tumor progression but the mechanism of downregulation remains to be elucidated." (PMID 25490036, 2014). "A nonsense mutation was confirmed at codon 120, exon 3 (R120*) in the VHL gene, present in the blood, normal kidney tissue and all tumor regions." (PMID 25159823, 2014). "This is consistent with previous findings that PBRM1 mutations likely represent the second genetic event in tumor initiation after loss of VHL." (PMID 25124064, 2014). "The most common type (∼75% of cases) is the histologically defined clear cell renal cell carcinoma (CCRCC) that is closely associated with loss/inactivation of the von Hippel-Lindau (VHL) tumor suppressor gene." (PMID 24454902, 2014). "In conclusion, our study report novel findings showing that PLA2R1 is repressed in RCC by the loss of VHL tumor suppressor and the activation of the oncogenic HIF2α-c-MYC pathway and that repression favors RCC tumorigenecity." (PMID 24657971, 2014). "Most RCC result from Von Hippel-Lindau (VHL) tumor suppressor loss-of-function and subsequent gain-of-function of the oncogenic HIF-2alpha/c-MYC pathway." (PMID 24657971, 2014). "The hypoxia-inducible factor 1α (HIF1-α, encoded by HIF1A), the primary target of this complex, regulates over 80 genes associated with tumor progression, glycolysis, angiogenesis, and metastasis and is negatively regulated by the VHL elongin BC complex." (PMID 25298778, 2014). "The VHL gene has the characteristics of a classic tumor suppressor gene; i.e., loss of the wild type allele in CNS HB patients with VHL, and somatic mutations in sporadic CNS HB with a loss of heterozygosity." (PMID 28326249, 2014). "A VHL mutation was detected in nine tumors (64%), each time being present ubiquitously throughout the tumor." (PMID 25124064, 2014). "In familial cases, genetic testing can detect VHL gene mutations in peripheral blood or tumor tissue." (PMID 28326249, 2014). "In tumors developing from a germline VHL mutation, the evolutionary principles of contingency and convergence in tumor development are complementary." (PMID 25159823, 2014). "Among the hybrid tumor 03 cases with foci of clear cells show VHL mutation while a single case showing combination of clear cells and chromophobe cells was negative for mutation." (PMID 25097537, 2014). "Multivariate analysis also showed that low VHL expression was independently associated with classical papillary growth pattern (OR = 2.92, 95% CI 1.33–6.44, P = 0.008) and tumor multifocality (OR = 1.96, 95% CI 1.06–3.62, P = 0.031)." (PMID 25490036, 2014). "Over time, germline mutations in VHL patients, as well as somatic mutations in different tumors, were identified, and its ability to act as a tumor suppressor in vivo were confirmed." (PMID 25091575, 2014). "In summary, our study shows that low VHL expression is associated with more aggressive tumor features of PTC and thus opens a new perspective for research into the role of VHL inactivation in PTC progression." (PMID 25490036, 2014). "PCC are frequently inherited through predisposing mutations in genes such as the von Hippel-Lindau (VHL) tumor suppressor." (PMID 25298778, 2014). "PLA2R1 expression correlates with loss of VHL tumor-suppressor function, and restoring VHL expression is sufficient to restore PLA2R1 expression in RCC-derived cell lines." (PMID 24657971, 2014). "In this small set of patients with early stage VHL-associated tumors, there is reduced mutation burden and limited evidence of intra-tumor heterogeneity." (PMID 25159823, 2014). "In the kidney, loss of the remaining wild-type VHL allele, consistent with a ‘two-hit’ model of tumor suppressor inactivation, results in multiple pre-neoplastic cysts and ccRCC tumors." (PMID 25159823, 2014). "Inactivating mutations of the VHL tumor suppressor gene caused the VHL cancer syndrome and sporadic ccRCC." (PMID 25091575, 2014).
tumor (continued). "In fact, for the VHL gene all 7 of the probes associated with VHL occur downstream of the CpG with only the closest probe demonstrating frequent tumor-specific hypermethylation." (PMID 24454902, 2014). "CCRCC has a very strong association with the tumor-specific loss of chromosome 3p and mutation/inactivation, including promoter hypermethylation, of the VHL gene on the remaining chromosome." (PMID 24454902, 2014). "We therefore examined the association between the VHL gene alteration status (intragenic mutation and promoter hypermethylation) and the tumor expression of PTHLH in selected clear cell RCCs (n = 244)." (PMID 24861371, 2014). "High depth sequencing was required to unmask the low allelic fraction of VHL mutations and copy number alterations found in the neoplastic “stromal” cells, which are present only in a fraction of cells comprising the overall tumor mass." (PMID 25589003, 2014). "This type of cancer develops in the renal proximal tube and is linked to biallelic inactivation of the von Hippel–Lindau (VHL) tumour suppressor gene." (PMID 23785518, 2013). "The protein encoded by the VHL gene is a tumor-suppressor and part of an E3 ubiquitin ligase complex that targets the hypoxia-inducible factor 1α (HIF-1α) for ubiquitination and proteasomal degradation." (PMID 24086736, 2013). "These included sites in genes that encode caspases (CASP8 and CASP10) and the von Hippel-Lindau (VHL) tumor suppressor, which have been implicated in various cancers." (PMID 24183664, 2013). "The von Hippel–Lindau (VHL) tumour suppressor gene is mutated, deleted or epigenetically silenced in up to 85% of all sporadic cases of ccRCC." (PMID 23606570, 2013). "VHL disease is due to germline mutation in the VHL tumour suppressor gene, which is located on the short arm of chromosome 3." (PMID 24062953, 2013). "TMEM74 is known to regulate autophagy and though it has not been implicated previously in RCC, it is interesting to note that the tumour suppressor activity of the VHL TSG has been linked to regulation of autophagy." (PMID 24034811, 2013). "VHL loss conforms to the Knudson 2-hit model that dictates that both wild-type alleles of a tumor suppressor gene must be inactivated prior to tumor outgrowth." (PMID 23628112, 2013). "This cancer is characterized by an early loss of VHL tumor suppressor on the short arm of chromosome 3 in the majority of tumors (80%)." (PMID 23922894, 2013). "Von Hippel-Lindau (VHL) disease is an autosomal dominant inheritable disorder characterized by the inactivation of VHL tumor suppressor gene due to mutations in VHL gene." (PMID 23028796, 2012). "Consistent with the role of HIF in cancer, introduction of VHL into VHL-deficient RCCs suppresses tumor formation in mice." (PMID 22295124, 2012). "We have examined the expression of VHL mutant RNA in 84 ccRCC tumours previously screened for mutations in genomic DNA, 56 of which contained 52 unique mutations or polymorphisms." (PMID 22825683, 2012). "In VHL-deficient cells, HIFs are constitutively active and induce target genes that promote tumor progression." (PMID 22295124, 2012). "Our data suggest that in the majority of RCC tumours in which VHL has a truncating mutation, even if the PTC is located before the 50–54 nt boundary, mutant mRNA is present, albeit at a reduced level in some tumours." (PMID 22825683, 2012). "In our previous study with 74.6% of RCC cases having a detectable VHL mutation and 31.3% methylation of the VHL promoter, 32 tumours had both mutation and methylation and of these, 30 also had LOH." (PMID 22825683, 2012). "The causal gene, VHL, is located on chromosome 3p26-25 and is known to act as a tumor-suppressor gene." (PMID 22462637, 2012).
tumor (continued). "The CXCR4 gene can further be transactivated by the activation of HIF-1α, arising from either loss of von-Hippel-Lindau tumor suppressor (VHL) or due to the hypoxic conditions observed frequently in tumor tissues." (PMID 24212934, 2011). "The OR associated with having a ccRCC tumor with a genetic VHL inactivating alteration decreased in a dose-dependent manner among former [OR = 0.70(0.20–1.31)] and current smokers [OR = 0.56(0.32–0.99)] compared to never smokers (p-trend = 0.04)." (PMID 22022277, 2011). "Low fruit intake frequency was associated with having a VHL promoter hypermethylated tumor (p = 0.02)." (PMID 22022277, 2011). "Germline VHL SNPs and a haplotype were associated with promoter hypermethylation in tumor tissue (OR = 6.10; 95% CI: 2.28–16.35, p = 3.76E-4, p-global = 8E-5)." (PMID 22022277, 2011). "The global p-values indicated that germline variation across the VHL gene region was significantly associated with risk of having a VHL hypermethylated tumor." (PMID 22022277, 2011). "A recent article by Gordan addressed this crucial question and suggested that HIF2 enhances c-MYC activity and promotes tumor progression in VHL deficient tumors." (PMID 21756335, 2011). "Multivariate analysis of chromosome 3p loss revealed that the only patient/tumor characteristic or RCC risk factor associated with 3p or clone CTB110j24 loss was inactivation of the VHL gene, and the association was highly significant." (PMID 22022277, 2011). "von Hippel-Lindau (VHL) tumor suppressor gene inactivation plays a causal role in the pathogenesis of ccRCC." (PMID 21949687, 2011). "Only tobacco smoking and fruit intake, were significantly associated with VHL genetic inactivation in tumor tissue, and/or were required for adjustment." (PMID 22022277, 2011). "The second region associated with promoter hypermethylation in tumor DNA was centered 3′ to the VHL stop codon." (PMID 22022277, 2011). "When compared to the most common SNP or haplotype as a common referent, subsequent analyses revealed that several individual SNPs and two high risk haplotypes were associated with tumor-specific VHL promoter hypermethylation." (PMID 22022277, 2011). "The von Hippel-Lindau (VHL) tumor suppressor gene encodes a component of a ubiquitin ligase complex, which is best understood as a negative regulator of hypoxia inducible factor (HIF)." (PMID 21386990, 2011). "The most significant global association across all inherited haplotype variants and tumor-specific VHL promoter hypermethylation was observed when a 9-SNP window spanning across the entire VHL gene region was evaluated." (PMID 22022277, 2011). "The most common of the hereditary syndromes are germline mutations in the von Hippel–Lindau (VHL) tumour-suppressor gene on chromosome 3p, which is associated exclusively with the clear cell histological subtype." (PMID 20442711, 2010). "In RCC, the loss of function of the Von Hippel Lindau (VHL) tumor supressor gene mediates up-regulation of CXCR4 which then promotes tumor spread and progression." (PMID 20819239, 2010). "Previous studies have shown that VHL can be Neddylated on lysine 159 to associate with fibronectin matrix assembly and suppression of tumor development, however, this posttranslational modification is not related to its E3 ligase activity." (PMID 20300531, 2010). "The best-characterized function of VHL is as an adaptor for targeting HIFα for proteolytic degradation, and has been considered to be the major tumor suppressor activity associated with VHL." (PMID 20300531, 2010). "The overexpression of HIFα alone is insufficient to induce tumor formation in some cases, and genetic mutation of VHL leads to a range of human diseases." (PMID 20300531, 2010). "In this pilot study we evaluated the feasibility of vaccination against mutant VHL peptides corresponding to the patients' own tumor mutations." (PMID 20109232, 2010).